Y_RNA (Y RNA )
Gene: Miscellaneous RNA gene on chromosome 12 (130,906,838 to 130,906,949, forward strand). Ensembl gene ENSG00000206850.
Homologues: Orthologues: chimpanzee Y_RNA (97% identical), macaque Y_RNA (91% identical). Paralogues in human: Y_RNA (85% identical), RNY1P5 (84% identical), Y_RNA (84% identical), RNY1 (83% identical), Y_RNA (83% identical), Y_RNA (82% identical), Y_RNA (81% identical), RNY1P11 (80% identical), Y_RNA (80% identical), RNY1P8 (79% identical), Y_RNA (79% identical), RNY1P7 (79% identical), and 94 more.